CFAP161 (cilia and flagella associated protein 161)
Description:
Microtubule inner protein (MIP) part of the dynein-decorated doublet microtubules (DMTs) in cilia axoneme, which is required for motile cilia beating.
Synonyms: C15orf26; FLJ38615
Tractability: Small molecule: a structure with a bound ligand is known.
Gene: Protein-coding gene on chromosome 15 (81,007,033 to 81,149,179, forward strand). Ensembl gene ENSG00000156206.
Subcellular location: Cytoplasm, cytoskeleton, cilium axoneme; Cytoplasm, cytoskeleton, flagellum axoneme
Gene Ontology:
Molecular function: protein binding
Biological process: cilium assembly; flagellated sperm motility
Cellular component: axonemal microtubule; axonemal A tubule inner sheath; motile cilium; sperm flagellum; axoneme
Genetic constraint (gnomAD): Loss-of-function variants: 15 observed, 22.44 expected, observed/expected ratio (o/e) 0.67, 90% interval 0.45 to 1.03. The upper end of that interval is the gene's LOEUF score, 1.03, which puts it in group 4 of 6, group 1 being the genes least tolerant of losing a copy. Missense variants: 351 observed, 362.43 expected, observed/expected ratio (o/e) 0.97, 90% interval 0.89 to 1.06. Synonymous variants: 114 observed, 136.12 expected, observed/expected ratio (o/e) 0.84, 90% interval 0.72 to 0.98.
Homologues: Orthologues: chimpanzee CFAP161 (99% identical), macaque CFAP161 (96% identical), rabbit CFAP161 (83% identical), dog CFAP161 (82% identical), pig CFAP161 (78% identical), mouse Cfap161 (73% identical), guinea pig CFAP161 (72% identical), rat Cfap161 (70% identical), tropical clawed frog cfap161 (47% identical), zebrafish cfap161 (42% identical), Drosophila melanogaster CG34457 (26% identical), Drosophila melanogaster CG15498 (24% identical).
Diseases named in the same sentence as CFAP161 in open-access papers:
CFAP161 is named in the same sentence as 4 diseases in open-access papers, as found by Europe PMC text mining. Sharing a sentence is not in itself a finding about the gene and the disease. The quoted sentences say what the papers report.
Kartagener Syndrome (1 paper, 2022). An autosomal recessive disorder characterized by a triad of DEXTROCARDIA; INFERTILITY; and SINUSITIS. "CFAP161, located on chromosome 15q in the linkage region of Kartagener syndrome, was only studied in mice and Xenopus." (PMID 35831825, 2022).
CFAP161 also shares sentences with these, for which no sentence is quoted: ciliopathies (2 papers); asthma (1); Hydrocephalus (1).